KRIT1 (KRIT1 ankyrin repeat containing)
Description:
Component of the CCM signaling pathway which is a crucial regulator of heart and vessel formation and integrity (By similarity). Negative regulator of angiogenesis. Inhibits endothelial proliferation, apoptosis, migration, lumen formation and sprouting angiogenesis in primary endothelial cells. Promotes AKT phosphorylation in a NOTCH-dependent and independent manner, and inhibits ERK1/2 phosphorylation indirectly through activation of the DELTA-NOTCH cascade. Acts in concert with CDH5 to establish and maintain correct endothelial cell polarity and vascular lumen and these effects are mediated by recruitment and activation of the Par polarity complex and RAP1B. Required for the localization of phosphorylated PRKCZ, PARD3, TIAM1 and RAP1B to the cell junction, and cell junction stabilization. Plays a role in integrin signaling via its interaction with ITGB1BP1; this prevents the interaction between ITGB1 and ITGB1BP1. Microtubule-associated protein that binds to phosphatidylinositol 4,5-bisphosphate (PIP2)-containing membranes in a GTP-bound RAP1-dependent manner. Plays an important role in the maintenance of the intracellular reactive oxygen species (ROS) homeostasis to prevent oxidative cellular damage. Regulates the homeostasis of intracellular ROS through an antioxidant pathway involving FOXO1 and SOD2. Facilitates the down-regulation of cyclin-D1 (CCND1) levels required for cell transition from proliferative growth to quiescence by preventing the accumulation of intracellular ROS through the modulation of FOXO1 and SOD2 levels. May play a role in the regulation of macroautophagy through the down-regulation of the mTOR pathway.
Synonyms: CCM1; CAM
Tractability: Small molecule: a structure with a bound ligand is known. Antibody: its Gene Ontology location is reachable by antibodies, with high confidence; UniProt places it where antibodies can reach, with medium confidence. PROTAC: ubiquitination databases record sites on it; its protein half-life has been measured.
Gene: Protein-coding gene on chromosome 7 (92,197,498 to 92,246,166, reverse strand). Ensembl gene ENSG00000001631.
Subcellular location: Cytoplasm, cytoskeleton; Cell membrane; Cell junction
Subcellular location (Human Protein Atlas): Vesicles
Gene Ontology:
Molecular function: microtubule binding; phosphatidylinositol-4,5-bisphosphate binding; protein binding; GTPase regulator activity
Biological process: cell redox homeostasis; integrin activation; negative regulation of angiogenesis; negative regulation of endothelial cell apoptotic process; negative regulation of endothelial cell migration; negative regulation of endothelial cell proliferation; regulation of establishment of cell polarity; endothelium development; regulation of angiogenesis; small GTPase-mediated signal transduction
Cellular component: cell-cell junction; extracellular region; plasma membrane; anchoring junction; cytoplasm; cytoskeleton; protein-containing complex
Genetic constraint (gnomAD): Loss-of-function variants: 14 observed, 31.71 expected, observed/expected ratio (o/e) 0.44, 90% interval 0.29 to 0.69. The upper end of that interval is the gene's LOEUF score, 0.69, which puts it in group 2 of 6, group 1 being the genes least tolerant of losing a copy. Missense variants: 299 observed, 344.37 expected, observed/expected ratio (o/e) 0.87, 90% interval 0.79 to 0.96. Synonymous variants: 104 observed, 110.68 expected, observed/expected ratio (o/e) 0.94, 90% interval 0.8 to 1.11.
Homologues: Orthologues: chimpanzee KRIT1 (99% identical), macaque KRIT1 (99% identical), dog KRIT1 (99% identical), rabbit KRIT1 (99% identical), pig KRIT1 (98% identical), guinea pig KRIT1 (97% identical), rat Krit1 (95% identical), mouse Krit1 (95% identical), tropical clawed frog krit1 (85% identical), zebrafish krit1 (78% identical), Caenorhabditis elegans kri-1 (23% identical). Paralogues in human: FRMD8 (13% identical).
Diseases named in the same sentence as KRIT1 in open-access papers:
KRIT1 is named in the same sentence as 64 diseases in open-access papers, as found by Europe PMC text mining. Sharing a sentence is not in itself a finding about the gene and the disease. The quoted sentences say what the papers report.
cerebral cavernous malformation (71 papers, 2010 to 2026). A disorder characterized by malformations in the structure of the capillaries in the brain. "Mutations in human KRIT1 underlie cerebral cavernous malformations, a disease marked by defects in vascular integrity." (PMID 42239296, 2026). "Cerebral cavernous malformation (CCM) is a vascular disease caused by mutations in the CCM1/KRIT1, CCM2, or CCM3/PDCD10 genes." (PMID 39402138, 2024). "KRIT1 gene germline pathogenic deleterious variants are causative for cerebral cavernous malformations." (PMID 38664609, 2024). "Subsequently named Krev1/Rap1a Interaction Trapped, Krit1 was mapped initially to chromosome 7q21-22, where a gene mutated in Cerebral Cavernous Malformations (CCM) had recently been mapped." (PMID 38980708, 2024). "The capillary-venous pathology cerebral cavernous malformation (CCM) is caused by loss of CCM1/Krev interaction trapped protein 1 (KRIT1), CCM2/MGC4607, or CCM3/PDCD10 in some endothelial cells." (PMID 37019926, 2023). "KRI1 is an ortholog of KRIT1, and KRIT1 mutation has been identified in cerebral cavernous malformations." (PMID 35813863, 2022). "KRIT1 loss-of-function mutations underlie the pathogenesis of Cerebral Cavernous Malformation (CCM), a major vascular disease affecting the central nervous system (CNS)." (PMID 36232456, 2022). "Cerebral cavernous malformations are associated with mutations in three genes: CCM1/KRIT1 (krev interaction trapped-1) (MIM#604214), CCM2/MGC4607 (malcavernin) (MIM#607929), and CCM3/PDCD10 (programmed cell death 10) (MIM#609118)." (PMID 33651268, 2021). "Loss-of-function mutations in the KRIT1 gene are associated with the pathogenesis of cerebral cavernous malformations (CCMs), a major cerebrovascular disease still awaiting therapies." (PMID 30658464, 2019). "Cerebral cavernous malformation (CCM) is an inherited vascular disease that occurs when a second somatic mutation causes a loss of CCM1/KRIT1, CCM2, or CCM3 proteins." (PMID 29364115, 2018). "Heterozygous loss of KRIT1 in humans has been linked to the pathogenesis of Cerebral Cavernous Malformation (CCM), a major cerebrovascular disease of proven genetic origin affecting 0.3–0.5% of the population." (PMID 28811547, 2017). "Cerebral cavernous malformations are fragile blood vessel conglomerates in the central nervous system that are caused by mutations in the CCM1/KRIT1, CCM2 or CCM3 genes." (PMID 26698571, 2015). "Loss-of-function mutations of the KRIT1 gene (CCM1) have been associated with the Cerebral Cavernous Malformation (CCM) disease, which is characterized by serious alterations of brain capillary architecture." (PMID 22970292, 2012). "Here, we demonstrate that KRIT1, a protein whose loss-of-function has been associated to the pathogenesis of the vascular disease Cerebral Cavernous Malformations, is part of the intracellular machinery that controls the redox balance." (PMID 20668652, 2010). "Loss-of-function mutations in KRIT1 lead to the development of cerebral cavernous malformations (CCM), a disease marked by the formation of abnormal blood vessels which exhibit a loss of barrier function, increased endothelial proliferation, and altered gene expression." (PMID 38980708, 2024). "Notably, two previously unreported variants, KRIT1 p.E379* in a familial cerebral cavernous malformation and F2 p.F382L in familial cerebral venous sinus thrombosis, were disclosed." (PMID 36580209, 2023). "Cerebral Cavernous Malformations (CCM) are often caused by mutations in CCM1/KRIT1." (PMID 30996251, 2019). "Cerebral cavernous malformations are characterized by the presence of vascular lesions that are most prevalent in the brain and can occur sporadically or through a familial condition from mutations in CCM1/KRIT1, CCM2/Malcavernin, or CCM3/PDCD10 [reviewed in]." (PMID 30181117, 2018).
cerebral cavernous malformation (continued). "While it is primarily recognized for its association with Cerebral Cavernous Malformations (CCMs), KRIT1 may also play critical roles in tumor formation and the acquisition of malignant phenotypes, regulating cell adhesion, cytoskeletal dynamics, and angiogenesis." (PMID 42074063, 2026). "Familial forms of the human vascular disease, cerebral cavernous malformation (CCM), arises from mutation in any of three genes (CCM1/KRIT1, CCM2/Malcavernin, and CCM3/PDCD10)." (PMID 36653023, 2023). "Loss of KRIT1 expression leads to the development of cerebral cavernous malformations (CCM), abnormalities characterized by leaky, enlarged (‘cavernous’) microvascular lesions in the brain and other tissues." (PMID 34918736, 2022). "Loss-of-function mutations of the KRIT1 gene have been clearly associated with the pathogenesis of cerebral cavernous malformation (CCM), a major vascular disorder affecting capillaries." (PMID 33443102, 2021). "Loss-of-function mutations are known in one of the three CCM genes: Krev interaction trapped 1 (CCM1/KRIT1), cerebral cavernous malformations 2 (CCM2) and programmed cell death 10 (PDCD10) predisposes to CCMs5,6." (PMID 31796831, 2019). "Loss of KRIT1 leads to decreased microvessel barrier function and to the development of the vascular disorder Cerebral Cavernous Malformation (CCM)." (PMID 28811547, 2017). "KRIT1 was originally identified through a yeast two-hybrid screening designed to find interacting partners of the Ras-like GTPase Rap1, and subsequently found to be one out of three genes responsible for causing Cerebral Cavernous Malformations (CCM; OMIM 116860)." (PMID 20668652, 2010). "The endothelial CCM (Cerebral Cavernous Malformation) complex, comprising KRIT1 (Krev1 interaction trapped gene 1), CCM2 (Malcavernin), and CCM3 (Programmed cell death protein 10), suppresses the expression of KLF2 and KLF4." (PMID 40362576, 2025). "The PDCD10 gene encodes the highly conserved PDCD10 adaptor protein that forms a protein complex with other cerebral cavernous malformation (CCM) disease–associated proteins, KRIT1 and CCM2, in endothelial cells to maintain vessel integrity." (PMID 34156031, 2021). "Mutations in the genes KRIT1, CCM2, and PDCD10 are known to result in the formation of cerebral cavernous malformations (CCMs)." (PMID 27896269, 2016). "Mutations in CCM1 (aka KRIT1), CCM2, or CCM3 (aka PDCD10) gene cause cerebral cavernous malformation in humans." (PMID 27513872, 2016). "In vitro studies have implicated KRIT1/CCM1, a protein mutated in cerebral cavernous malformations (CCM), RASIP1 and an actin-cytoskeleton linker Canoe/Afadin as Rap1 effectors controlling cell-cell junction formation and maintenance." (PMID 26714318, 2015). "KRIT1 is a gene responsible for Cerebral Cavernous Malformations (CCM), a major cerebrovascular disease characterized by abnormally enlarged and leaky capillaries that predispose to seizures, focal neurological deficits, and fatal intracerebral hemorrhage." (PMID 20668652, 2010). "As a key regulator of endothelial cell functions, KRIT1 is critically involved in cerebral cavernous malformation (CCM), a cerebrovascular disorder characterized by leaky, dilated vascular clusters, which can lead to seizures, neurological impairments, and intracerebral hemorrhage." (PMID 41009024, 2025). "Importantly, we disclosed two previously unreported PVs, KRIT1 p.E379* in a familial cerebral cavernous malformation, and F2 p.F382L in a familial cerebral venous sinus thrombosis." (PMID 36580209, 2023).
cerebral cavernous malformation (continued). "Notably, we identified two novel PVs, KRIT1 p.E379* in a family of cerebral cavernous malformation-related ICH, and F2 p.F382L in a family of cerebral venous thrombosis-related stroke, respectively." (PMID 36580209, 2023). "Indeed, we observed dysregulation of KRIT1, related to cerebral cavernous malformations (CCM), APLN, related to lymphatic malformations, GNA11 related to capillary malformations and BMPR2, related to arteriovenous malformations and hereditary pulmonary arterial hypertension (HHT)." (PMID 38771392, 2024). "Mutations in the cerebral cavernous malformation (CCM) genes, KRIT1, CCM2, and PDCD10, cause CCM disease." (PMID 36692953, 2023). "The set includes images of the control cells (wild-type HUVEC) and cells with knockdown (KD) of the three Cerebral Cavernous Malformation (CCM) proteins, CCM1 (or KRIT1), CCM2, and CCM3 (or PDCD10), which disrupts the integrity of multicellular mesh." (PMID 32881897, 2020). "Great progress has been made during the last decade in understanding the biological roles of the three known CCM proteins—KRIT1, CCM2, and CCM3—and their role in the pathogenesis of cerebral cavernous malformation (CCM) disease, revealing stunning complexity." (PMID 30658464, 2019). "Another possible intermediate molecule for integrin activation is Krev interaction trapped protein-1 (KRIT1)/cerebral cavernous malformation 1 (CCM1), of which autosomal dominant loss-of-function mutation causes CCM, because of compromised junctional integrity in endothelial cells." (PMID 29659486, 2018).
cavernomas (13 papers, 2014 to 2025). "Cavernomas appear sporadically (1:200) or as an autosomal dominant (1:10,000) loss-of-function germline mutation of KRIT1 (CCM1), Malcavernin (CCM2), or PDCD10 (CCM3) in endothelial cells of the CNS." (PMID 36293431, 2022). "Familial disposition is seen up to 50% with an autosomal dominant inheritance and loss of CCM1 (also known as KRIT1) protein was found to be an important factor in the development of cavernomas." (PMID 29326642, 2017). "We disclosed a novel stop-gain variant, KRIT1 p.E379* in a 63-year-old man with multiple CCMs presented as recurrent ICH and cavernoma-related epilepsy." (PMID 36580209, 2023). "Cavernous hemangiomas may occur sporadically or be inherited, with the latter associated with loss-of-function mutations in the KRIT1/CCM1, CCM2, or PDCD10/CCM3 genes." (PMID 40963940, 2025).
cerebrovascular disease (7 papers, 2010 to 2025). "The NGS data analysis was performed in two steps: initially we considered the three known CCM genes, namely KRIT1 (CCM1), CCM2 and PDCD10 (CCM3), and subsequently extended the analysis to NGS panels, including the “Cerebro” panel composed of 23 genes associated with cerebrovascular diseases." (PMID 35883785, 2022).
endothelial dysfunction (6 papers, 2019 to 2025). In vascular diseases, endothelial dysfunction is a systemic pathological state of the endothelium (the inner lining of blood vessels) and can be broadly defined as an imbalance between vasodilating and vasoconstricting substances produced by (or acting on) the endothelium. "We demonstrate that targeting endothelial KRIT1 initiates a protective response in endothelial cells exposed to disturbed flow patterns, which helps prevent the onset of an atheroprone gene program associated with endothelial dysfunction." (PMID 40362576, 2025). "Furthermore, this animal model has also allowed the identification of systemic effects caused by loss of heterozygous function mutations in KRIT1, including enhanced susceptibility to endothelial dysfunction and atherosclerosis." (PMID 36232456, 2022). "To address this possibility, we investigated whether KRIT1 deficiency causes endothelial dysfunction (ED), a critical early step and a predictor of atherosclerosis development." (PMID 31590384, 2019).
intracerebral hemorrhage (6 papers, 2010 to 2025). A cerebrovascular disorder characterized by bleeding into one or both cerebral hemispheres including the basal ganglia and the cerebral cortex. "For instance, while deleterious variants in KRIT1 and NOTCH3 are well-known causes of intracerebral hemorrhage and strokes, respectively, the recognition of new KRIT1 variants and rare NOTCH3 variants, such as p.R544C for ischemic small vessel disease, highlights the precision of WES." (PMID 39523358, 2024). "Across subtypes, the highest hit rate (HR) was intracerebral hemorrhage (ICH, 7/18 = 38.9%), particularly with the etiological subtype of structural vasculopathy (4/4 = 100%, PVs in ENG, KRIT1, PKD1, RNF213); followed by ischemic small vessel disease (SVD, 15/48 = 31.3%; PVs in NOTCH3, HTRA1, HBB)." (PMID 36580209, 2023). "The condition is caused by mutations in KRIT1 (CCM1), CCM2 (malcavernin), or PDCD10 (CCM3) and may lead to intracerebral hemorrhage (ICH) or non-hemorrhagic focal neurological deficits (FNDs), potentially leading to severe disability and even death." (PMID 41561324, 2025).
melanoma (6 papers, 2021 to 2026). A malignant, usually aggressive tumor composed of atypical, neoplastic melanocytes. "miR-21 mediated silencing of KRIT1 increases anchorage independent growth of MC-1 melanoma cells and MDA MB-231 breast cancer cells." (PMID 38980708, 2024). "KRIT1 deletion in A375 melanoma cells led to increased proliferation, migration, and invasion, increased localization of β-catenin in the nucleus, and increased expression of markers of epithelial-to-mesenchymal transition." (PMID 38980708, 2024). "By using a yeast two-hybrid screening, we identified Kinesin Family Member 1C (KIF1C), a protein involved in regulating podosome and invadopodium elongation, as a novel binding partner of KRIT1, and the interaction was confirmed in melanoma and epithelial cancer cells." (PMID 42074063, 2026). "Additionally, KRIT1 was recently reported to control the progression of melanoma by acting as a tumor suppressor, suggesting the role of KRIT1 in human cancer." (PMID 35813863, 2022).